RAC1 (Rac family small GTPase 1)
Diseases named in the same sentence as RAC1 in open-access papers (continued):
Sharing a sentence is not in itself a finding about the gene and the disease.
lymph node metastasis (9 papers, 2010 to 2024). "In line with our results, previous evidence has shown that the upregulation of RAC1 is associated with lymphovascular invasion and lymph node metastasis of the urinary tract cancer." (PMID 37147328, 2023). "We additionally crafted ROC curves and computed AUC scores to investigate the potential of Rac1 as a biomarker for prognosticating lymph node metastasis, yielding an AUC value of 0.638." (PMID 38344200, 2024). "In the metastatic setting, an increased RAC1 GTP-ase protein has been observed in 100% of lymph node metastases." (PMID 27902969, 2017). "The Rac1 expression rate in lymph node metastasis was 75 percent, which is significantly higher than in the group without metastasis (51%)." (PMID 23298303, 2014). "Rac1, Pak1 and Rock1 expression in the lymph node metastasis group (75, 71 and 66%) were significantly higher than in the group without metastasis (51, 43 and 41%)." (PMID 23298303, 2014). "Rac1 activity and Pak1 expression were higher in the primary tumors of patients with postoperative lymph node metastasis than in those of patients with bladder recurrence from the LVI(+) group, but not the LVI(-) group." (PMID 20426825, 2010). "Moreover, the high expression of Rac-1 is significantly correlated with advanced tumor depth, lymph node metastasis, and shorter disease-free and survival time." (PMID 30971268, 2019). "However, it is unclear whether Rac1 and Pak1 play a similar role in lymph node metastasis and bladder recurrence." (PMID 20426825, 2010). "The overexpression of RAC1 was related to poor differentiation, high TNM stage, and lymph node metastasis in NSCLC patients, while down-regulation of RAC1 can reduce cell migration and invasion and sensitize cells to antitumor drugs." (PMID 32848724, 2020). "A high level of Rac1 activity and Pak1 protein expression in the primary tumor was related to poor differentiation (P < 0.05), muscle invasion (P < 0.01), LVI (P < 0.0001), and lymph node metastasis (P < 0.0001)." (PMID 20426825, 2010).
metastatic cancer (9 papers, 2015 to 2025). A carcinoma which has spread from the original site of growth to another anatomic site. "The T-SNE plot of single cells from 8 patients showed that cells were clustered into 12 stable subgroups, among with RAC1 was highly expressed in the metastatic cancer cells." (PMID 37202394, 2023). "In doing so, pY14-CAV1 levels increase to favor migration and the invasion via Rab5/Rac1 activation in metastatic cancer cells." (PMID 35740528, 2022). "In metastatic cancer cells, activation of the small GTPase Rac-1, required for CAV1 to promote cell migration and invasion, involves upstream activation of Rab-5, another small GTPase." (PMID 32152405, 2020). "Instead EHop-016 blocks Rac1-Vav2 binding and has been shown to suppress Rac1-driven directed cell migration of metastatic cancer cells." (PMID 27442895, 2017). "The higher concentration of EH not only inhibit Rac1 but also Rac3 and Cdc42 in the MDA-MB-435 metastatic cancer cells." (PMID 26766136, 2016). "Not surprisingly, Rac1 and Cdc42 activity are often increased in highly motile cells and metastatic cancer." (PMID 25649192, 2015).
metastatic tumor (9 papers, 2014 to 2024). "We identified an acquired RAC1 (P34R) mutation in the metastatic tumor of a BRAF-mutated papillary thyroid cancer patient treated with the BRAF inhibitor dabrafenib." (PMID 34638434, 2021). "The frequency of RAC1 P29S mutation (overall RAC1 P29S mutation of 4.1%) was found to be more prevalent in male patients and similar between primary (9.2%) and metastatic tumors (8.6%)." (PMID 32850962, 2020). "Our findings indicate that loss of ΔNp63α is permissive for Rac1-dependent invasion in SCC, and this fits with the loss of ΔNp63α in advanced metastatic disease." (PMID 38191532, 2024). "Moreover, altering the balance of Rac1 to Rac1b expression and/or function towards Rac1b could represent a novel therapeutic approach in suppressing metastatic disease in PDAC and probably other carcinomas." (PMID 24378395, 2014).
squamous cell carcinoma (9 papers, 2014 to 2024). A carcinoma arising from squamous epithelial cells. "Overexpression and increased activity of the small Rho GTPase Rac1 has been linked to squamous cell carcinoma of the epidermis and mucosa in humans." (PMID 27506937, 2016). "ΔNp63α knockdown in multiple squamous cell carcinoma cell lines leads to increased Rac1 activation, which is abrogated by treatment with the Rac1 inhibitor NSC23766." (PMID 38191532, 2024). "The results indicated that Rac1 activation was involved in Rab23 promoted squamous cell carcinoma cells migration and invasion." (PMID 26716504, 2016). "Taken together, our results indicated that Rab23 promotes squamous cell carcinoma cells migration and invasion by regulating Integrin β1/Tiam1/Rac1 pathway." (PMID 26716504, 2016). "Surprisingly, we observed that, upon chronic UV-irradiation, the majority of mice with transgenic expression of HPV-8 and epidermis specific Rac1 deletion developed squamous cell carcinomas." (PMID 27506937, 2016). "The results indicated that Rab23 promotes squamous cell carcinoma cells migration and invasion requires activation of Rac1." (PMID 26716504, 2016). "Indeed, Rac1 showed a hyperproliferative-specific function in a genetically engineered keratinocyte restricted Rac1 deletion mouse model, and Rac1 expression was found to be elevated in papillomas and squamous cell carcinomas." (PMID 32351958, 2020). "Interestingly, MTSS1 was described to localize at junctions in kidney epithelium and squamous carcinoma cells through an I-BAR domain, and to be essential for maintenance of cell–cell adhesion by promoting Rac1 activation." (PMID 39404373, 2024). "Taken together, our data show that Rac1 exerts a dual role in skin carcinogenesis: its activation is, on one hand, required for HPV-8- and UV-light induced papilloma formation but, on the other, suppresses the development of squamous cell carcinomas." (PMID 27506937, 2016). "Furthermore, the presence of Rac1 is required to suppress the development of UV-light and HPV-8 induced squamous cell carcinomas." (PMID 27506937, 2016). "How can the absence of Rac1 promote the development of squamous cell carcinomas?" (PMID 27506937, 2016).
asthma (8 papers, 2016 to 2025). "Pharmacological inhibition of Rac1 in vivo prevented airway remodelling associated with asthma, confirming Rac1 as a promising therapeutic target for severe asthma." (PMID 41573715, 2025). "In this study, we explored the role of Nectin4 and its participation in Src/Rac1 signaling in asthma." (PMID 36457999, 2022). "The detection of a circulating form of Nectin4 in the blood of patients with asthma suggests the involvement of Nectin4 in the initiation of airway inflammation via a mechanism that includes the Src/Rac1 cascade pathway." (PMID 36457999, 2022). "Concerning "Workplace full of chemicals or other fumes: Sometimes" (with causal effect on “Condition that has ever been diagnosed by a doctor: Asthma”) the most statistically significant pathway involved is “NTRK2 activates RAC1”." (PMID 36395113, 2022). "Our results showed that, the expression levels of S1P2-SiRNA histone were decreased, indicating that S1P2 was involved in the development of asthma inflammation following the treatment with the RAC1 inhibitor EHT 1864." (PMID 33643037, 2020). "Previous lung studies had shown that apoptotic airway epithelial cells can be phagocytosed by other epithelial cells in a Rac1-dependent manner, at least in the context of asthma." (PMID 26811382, 2016). "Rac1 has been recently identified as an important player in the regulation of intracellular calcium and airway smooth muscle cell contraction, and its role as a therapeutic target in asthma is under evaluation." (PMID 35205259, 2022). "The RAC1 inhibitors could abrogate the therapeutic effects of JTE-013 in asthma." (PMID 33643037, 2020). "In our study, Src and Rac1 protein expression were increased in the lung tissue of a mouse model of asthma, and in NHBE cells treated with Der p1, indicating that Src/Rac1 signaling is involved in Nectin4 expression." (PMID 36457999, 2022). "Inhibiting Rac1-dependent signalling pathways concurrently reduced aSMC proliferation, airway hyperresponsiveness (AHR), and inflammation, presenting a novel approach to reverse airway remodelling and restore airway function in severe asthma patients." (PMID 41573715, 2025). "S1P is involved in the progression of asthma and airway remodeling, which may be related to the activation of S1PR2 receptor and inhibition of autophagy through RAC1." (PMID 33643037, 2020).
brain tumors (8 papers, 2010 to 2024). "P66Shc and Rac1 proteins are responsible for tumor-associated inflammation, particularly in brain tumors characterized by elevated oxidative stress and increased reactive oxygen species (ROS) production." (PMID 38362155, 2024). "Mutations in RAC1 allele are implicated in multiple brain tumors, indicating a rigorous control of Rac1 activity is required for neural tissue normal development and homeostasis." (PMID 34557485, 2021). "Specific studies on brain tumor models have unraveled some underlying mechanisms of RAC1-driven oncogenesis." (PMID 34943902, 2021). "In brain tumors, multiple mutations in RAC1 putative effector domain have been identified, suggesting a correlation between excessive RAC1 activity and brain tumorigenesis and abnormal development." (PMID 34557485, 2021). "One early study aiming to detect Rac1 mutations in human brain tumors identified deletions, frame shift and point mutations in 12 out of 45 samples from human patients with brain tumors, suggestive of a role for Rac1 in brain tumor development." (PMID 27104658, 2016). "In lieu of the achieved results, additional studies are required to understand the role(s) of quercetin on Rac1-p66Shc signaling to establish its role as a therapeutic drug particularly in brain tumors." (PMID 38362155, 2024). "The current study demonstrated that Ptx3 expression correlates with cell invasion via the NFκB pathway, regulating AHGEF7 and Rac1 expression in brain tumors." (PMID 36633805, 2023). "Accumulating scientific evidence has recently emerged in favor of a relevant involvement of Rac1 in cancer progression, especially in brain tumors." (PMID 34943902, 2021).
epilepsy (8 papers, 2011 to 2023). A brain disorder characterized by episodes of abnormally increased neuronal discharge resulting in transient episodes of sensory or motor neurological dysfunction, or psychic dysfunction. "Rac1 and Rac3 double mutants display a significant loss of parvalbumin-expressing INs in the cortex and hippocampus, leading to reduced spontaneous inhibitory currents (IPSCs) and epilepsy." (PMID 37779671, 2023). "In this study, we determined the amount of GLUN2B and GLUN2A, and assessed the activitity of CREB and Rac1 (downstream effectors of NMDARs) in healthy and epilepsy-prone rats following p-cresol treatment." (PMID 32455164, 2020). "The expression of Rac1 is significantly increased in the temporal lobe of patients with epilepsy and epilepsy model animals, suggesting that elevated Rac1 expression contributes to the pathophysiology of the disease." (PMID 32455164, 2020). "Thus, our data highlights a critical role for synaptic HAS2-HA-CD44 in protecting developing neural networks from the emergence of hyperexcitability and epilepsy through a RhoGTPase signaling axis, by suppressing aberrant Rac1 hyperactivation." (PMID 34685554, 2021). "In this study, we evaluated the expression of GLUN2B and GLUN2A NMDAR subunits, and assessed the activity of cAMP-response element binding protein (CREB) and Rac1 in the hippocampi and nucleus accumbens of healthy and epilepsy-prone rats following p-cresol administration." (PMID 32455164, 2020). "The pathological plasticity of neuronal spines and synapses is important in the pathological process of epilepsy; thus, we studied the activation levels of Rac1 and Cdc42 to explore whether Rac1 and Cdc42 are regulated by the miR-132/p250GAP pathway in our SRED model of cultured hippocampal neurons." (PMID 27579184, 2016).
Ewing sarcoma (8 papers, 2010 to 2025). A small round cell tumor that lacks morphologic, immunohistochemical, and electron microscopic evidence of neuroectodermal differentiation. "Given prior reports documenting upregulation of the IGF/IGF-1R axis with Ras/Rac1 signaling in Ewing sarcoma, we performed immunohistochemistry on tumors from the micro-metastatic in vivo experiment." (PMID 38534214, 2024).
fragile X syndrome (8 papers, 2016 to 2024). A genetic syndrome caused by mutations in the FMR1 gene which is responsible for the expression of the fragile X mental retardation 1 protein. "In addition, Rac1 has been found to be upregulated in fragile X syndrome, and rare genetic variants in Rac1 regulators have been found in ASD, BD and SZ." (PMID 30147856, 2018). "In a mouse model of Fragile X syndrome (FXS) the Rac1 GTPase pathway was shown to be hyperactive, causing a reduced activity of the actin-depolymerization and severing factor ADF/cofilin which in turn caused spine abnormalities." (PMID 29925821, 2018). "For example, the anomalous rise of rho GTPase Rac1 activity inhibited cofilin in mice with Fragile X syndrome because of a trinucleotide expansion in the FMR1 gene on the X chromosome." (PMID 34194309, 2021). "Differences in cAMP cascade have been previously reported in LCLs from patients diagnosed with Fragile X syndrome (FXS), for which an imbalance in the NRF2 and NF-κB pathways triggered by an over-activation of RAC1 can also be hypothesized." (PMID 38790952, 2024).
glomerular disease (8 papers, 2016 to 2022). "RhoA and Rac1 play key roles in regulating cytoskeletal dynamics in podocytes, and dysregulating the activity of these small GTPases in glomerular disease processes causes proteinuria." (PMID 35991898, 2022). "Alternatively, chronic Rac-1 activation or deletion specifically in podocytes, also causes proteinuria and glomerular disease, and Rac-1 appears to be essential to maintain the normal structure of endothelial cells in vivo." (PMID 27097314, 2016). "Indeed, RhoA and Rac1 play key roles in regulating cytoskeletal dynamics in podocytes, and dysregulated activity of these small GTPases in glomerular disease processes causes proteinuria." (PMID 31877991, 2019). "Ezrin seems to be associated with Rac1 activation when glomerular podocytes are injured, and the suppression of ezrin expression might thus be beneficial for protection of proteinuria in glomerulopathies." (PMID 29540766, 2018). "Prior work has shown that Rac1 activation is a nodal event in a spectrum of glomerular diseases, while inhibition of Rac1 activity ameliorates podocyte injury in response to various noxious stimuli." (PMID 34621762, 2021). "Rho GTPase family members such as RhoA, Rac1, and Cdc42 play key roles in glomerular disease processes." (PMID 31877991, 2019). "The Rac1 pathway has been studied intensely and has significant relevance to human glomerular diseases." (PMID 29567961, 2018). "Greka and colleagues hypothesized that unopposed and excessive Rac1 signaling might play a role in glomerular diseases by promoting maladaptive cytoskeletal remodeling and induce proteinuria." (PMID 31877991, 2019). "As Rac1 activation is the common pathway of podocyte effacement, FHL2 inhibition therefore should be effective not only in hypertensive nephropathy but also in other glomerular diseases." (PMID 31040292, 2019).
Nephropathy (8 papers, 2013 to 2025). A nonspecific term referring to disease or damage of the kidneys. "Previous studies have shown that high-glucose stimulation can cause RAC1 activation, lead to apoptosis, and aggravate kidney damage." (PMID 34194338, 2021). "The present study was designed to determine whether the common SNPs of the RAC1 gene are associated with diabetic complications such as neuropathy (DN), retinopathy (DR), nephropathy, angiopathy of the lower extremities (DA), and diabetic foot syndrome." (PMID 36979960, 2023). "In the context of tubule injury, Rac1 contributes to oxalate-induced nephropathy by increasing reduced form of nicotinamide adenine dinucleotide phosphate–mediated cell injury and it enhances transforming growth factor–β1–driven epithelial dysfunction in a UUO model." (PMID 38324689, 2024).